RNU6-5P (RNA, U6 small nuclear 5, pseudogene)
Synonyms: U6-5; RNU6-5
Gene: Small nuclear RNA gene on chromosome 2 (174,557,966 to 174,558,072, reverse strand). Ensembl gene ENSG00000206965.
Homologues: Orthologues: guinea pig U6 (100% identical), macaque U6 (100% identical), mouse Gm22580 (100% identical), mouse Gm22798 (100% identical), mouse Gm22822 (100% identical), mouse Gm23934 (100% identical), mouse Gm24722 (100% identical), rat U6 (100% identical). Paralogues in human: RNU6-1 (100% identical), RNU6-2 (100% identical), RNU6-3P (100% identical), RNU6-4P (100% identical), RNU6-6P (100% identical), RNU6-9 (100% identical), RNU6-12P (99% identical), RNU6-13P (99% identical), RNU6-17P (99% identical), RNU6-18P (99% identical), RNU6-25P (99% identical), RNU6-32P (99% identical), and 1288 more.